ICAM1 (intercellular adhesion molecule 1)
Diseases named in the same sentence as ICAM1 in open-access papers (continued):
Sharing a sentence is not in itself a finding about the gene and the disease.
infection (continued). "Affinity-selected scFv against hepatitis B virus also neutralized infection in vitro, and purified scFv that recognize intercellular adhesion molecule ICAM-1 effectively blocked transmission of HIV across an epithelial cell monolayer both in vitro and in a small animal model." (PMID 18237416, 2008). "Indeed, pre-infection in the peritoneum or LPS-treatment ip very rapidly activated the cerebral endothelium, elevating transcriptional expression of cell adhesion molecules, such as ICAM-1, in microvasculature." (PMID 40229286, 2025). "ICAM-1 is a glycoprotein constitutively present on the surface of various cells, including epithelial and endothelial cells, lymphocytes, and monocytes; an upregulation in response to specific stimuli, such as injury or infection, is mediated by cytokines (TNF-α, IFN-γ) or ROS." (PMID 38892239, 2024). "Endothelial cells from infected young mice displayed elevated expression of chemokines (Cxcl9, Ccl2) and leukocyte adhesion markers (Icam1) underscoring that inflammation of lung endothelium during infection could facilitate leukocyte adhesion and thromboinflammation." (PMID 38911865, 2024). "Hence, while ICAM-1 may be critical in the early stages of infection as part of an increased viral adsorption, it also induces an antiviral response in later stages of infection, contributing to a decrease in viral titers." (PMID 38892239, 2024). "On the other hand, the upregulation in inflammatory monocytes in the brain vasculature was only detected in infections with the virulent strain (1/148), suggesting that ICAM1 may play a role in disease severity, perhaps by favoring parasite sequestration and/or lymphocyte recruitment." (PMID 35787830, 2022). "Furthermore, whereas reduced numbers of virus specific effector CD8+ T cells accumulated inside infected ICAM-1/2-/- lungs, normal virus-specific TRM CD8+ cells were generated inside these lungs and fully protected ICAM-1/2-/- mice from secondary heterosubtypic infections." (PMID 36895258, 2022). "In addition, s-ICAM1 positively correlated with E-selectin (Spearman r 0.512) which are both related with the adhesion of the leukocytes to the endothelium at the site of infection." (PMID 35327327, 2022). "Furthermore, Orf virus and influenza virus infection enhanced the expression of ICAM-1 in mammals." (PMID 34489953, 2021). "Interestingly, we found that the expression of ICAM-1 was periodic after Ich infection." (PMID 34489953, 2021). "Taken together, although ICAM-1 is widely considered an indicator of endothelial activation, we believe it may also represent an important host target that can be induced by meningitic E. coli during infection." (PMID 31092253, 2019). "Indeed, in vitro studies have shown upregulation of ICAM-1 and VCAM-1 expression in human endothelial cells upon infection with myocarditis-associated viruses (adenovirus, arenavirus, coxsackievirus B3 (CVB3), cytomegalovirus, and West Nile virus) or upon infection with T. cruzi." (PMID 29536322, 2018). "In the context of ECM, a reduction of brain ICAM-1 protein expression was observed in the vasculature upon rapamycin treatment that could contribute to the reduction of parasite and leukocyte sequestration in this organ late in infection." (PMID 29121917, 2017). "Analysis of ICAM-1 expression in brain sections on day 6 post-infection revealed rapamycin-dependent reduction in the intensity of endothelial ICAM-1 expression as well as the total endothelial area expressing this adhesion molecule (CD31/ICAM-1 vascular co-localization)." (PMID 29121917, 2017).
infection (continued). "Therefore, L‐carbocisteine may inhibit RV14 infection in HNE cells partly by reducing ICAM‐1 levels and the number of acidic endosomes by inhibiting the activation of NF‐κB, as was previously reported in experiments using human tracheal epithelial cells." (PMID 27957326, 2016). "Alternatively, direct interaction of Y. pestis with endothelial cells might affect the expression of these molecules, as demonstrated for ICAM-1 during in vitro infection of human umbilical vein endothelial cells (HUVECs) with the related enteropathogen Y. enterocolitica." (PMID 25974210, 2015). "ICAM-1 is an essential component of leukocyte transmigration into sites of inflammation and suppression of the response could impair the ability of the immune response to control infection or repair injured tissues." (PMID 25888960, 2015). "The finding that ICAM-1 is incorporated into the rRABV-mICAM-1 particle may have implications for vaccine design since pre-treating rRABV-mICAM-1 particles with an ICAM-1 neutralizing antibody reduces B cell infection and activation to levels observed with rRABV alone." (PMID 24489846, 2014). "In addition, over-expression of TLRs and other PRRs on the surface of phagocytic cells, or activation of endothelial cells and expression of adhesion molecules, such as ICAM1 or e-Selectin, are also signals known to promote efficient localization of phagocytes to the site of infection/tissue damage." (PMID 23894499, 2013). "Similarly, in the present study, we found a marked increase in ICAM-1 expression in the brain on day 6 of infection, VCAM-1 and P-selectin had more modest increases and E-selectin expression was not significantly different in uninfected and saline-treated mice." (PMID 21649904, 2011). "Results were consistent with the in vitro findings, which showed that E44 infection could increase the expression of ICAM-1 and CD44 in wildtype mice, and that nicotine could amplify E44-induced expression of these two adhesion molecules in the wildtype animals." (PMID 21966399, 2011). "Given that ICAM-1 was differentially expressed on the apical surface of polarized epithelial cells, whilst transfer infection occurred at the basolateral surface, we re-examined the role of integrins, or other components of the extracellular matrix, in transfer infection." (PMID 21573183, 2011). "Blocking ICAM-1 resulted in the most significant reduction in adhesion (****p < 0.0001), highlighting its dominant role in Hib binding during HPIV3 infections." (PMID 40520162, 2025). "Contrary to expectations, gene expression of ICAM1 decreased to undetectable levels 2 h post-infection in HBMEC and 8 h post-infection in HUVEC." (PMID 40141288, 2025). "Blocking ICAM-1 and PAFr significantly reduced adherence upon RSV and HPIV3 infection to pre-infection levels of between 1 or 2-fold induction (**p < 0.01)." (PMID 40520162, 2025). "Notable exceptions included ADAMTS13, ICAM1, and MCP1, which showed reduced expression 2 h (ADAMTS13 and ICAM1) and 4 h (MCP1) post-infection, to below detectable levels by qPCR." (PMID 40141288, 2025). "Cytokine-mediated endothelial activation promotes the expression of adhesion molecules like E-selectin and intercellular adhesion molecule-1 (ICAM-1), facilitating the recruitment of neutrophils to sites of infection." (PMID 39594987, 2024). "Taking these experiments as basis, the infection alone would go almost unnoticed regarding the expression of HLA-ABC, HLA-DR, or ICAM-1." (PMID 39038032, 2024). "ICAM-1 and/or DAF cell surface receptors are responsible for the specific adhesion of CVA21 and subsequent infection of the host cell." (PMID 39539548, 2024). "An additional study showed that the intercellular adhesion molecule-1 (ICAM-1) and related cytokine molecules are induced by PIV3, and it is thought that this activation participates in the inflammation during infection by viruses." (PMID 38543591, 2024).
infection (continued). "Both isoforms stimulated the maturation of microvesicle-infected dendritic cells, with HSP90β being more potent than the former, and increased ICAM-1 expression, thereby facilitating HIV-1 transfer to T cells and enhancing the cell-to-cell spread of infection." (PMID 39308823, 2024). "After two days of infection with pOka-Δ57-GFP, we stimulated the cells with IFN-γ for another day and then quantified ICAM1 protein levels by flow cytometry." (PMID 38909022, 2024). "During infection the response to IL-2, including STAT5 phosphorylation and proliferation, is facilitated by cell clustering and LFA-1/ICAM-1 interaction." (PMID 39261466, 2024). "We detected some significantly upregulated proteins upon infection: IRG1, GBP5, ICAM1, ACSL1, and PDL1 independently on the presence or absence of SLAMF1." (PMID 39000601, 2024). "miR146a-5p was predicted to be a negative regulator of B. burgdorferi-induced inflammation in early infection with mRNA targets including TLR2, STAT1, ICAM1, and IL6." (PMID 37319241, 2023). "We used moderate multiplicity of infection (moi = 5) of Ad-PIMT to induce both HMW and LMW ICAM-1 and then performed co-IP." (PMID 37070640, 2023). "HBZ was previously shown to enhance HTLV-1 infection by activating the expression of ICAM1 and MYOF, and in this study, we found that HBZ upregulates two additional cellular genes involved in infection: COL4A1 and GEM." (PMID 37375521, 2023). "In order to compare the growth kinetics of HRV-B14 on Vero_ICAM1#4C4, Vero_ICAM1#9G4 and RD cells, these cell lines were infected with HRV-B14 (MOI 0.01) and samples at different days post-infection were titrated." (PMID 36298792, 2022). "Expression of ICAM-1, a ligand for the integrin LFA-1, was significantly upregulated in both WT and Tlr7−/y after infection, but the magnitude of upregulation remained substantially greater in WT mice (factor of ~3)." (PMID 36278864, 2022). "Of note, MP activation 36 hr post-infection, as measured by cell-surface modulation of MHC-II, CD80, ICAM-1, and Sca-1, was mostly comparable in all infected groups, likely ruling out a general activation defect of STING-deficient MP." (PMID 36278864, 2022). "In conclusion, through the expression of sG, RSV can blunt the activity of certain chemokines such as ICAM-1, IL-8, and RANTES, leading to a decreased recruitment of innate immune cells to the site of infection." (PMID 35216012, 2022). "Accordingly, in a murine model of H1N1 infection, treatment with 1,8-cineole inhibited the upregulation of ICAM-1 and VCAM-1 induced by infection, corroborating the anti-inflammatory effect of the compound." (PMID 35550638, 2022). "Interestingly, on day 4 post infection with PR8 encoding the OT-I cognate ligand, SIINFEKL, OT-I CD8+ T cells in the MedLNs of ICAM-1/2-/- mice proliferated and differentiated vigorously, whereas by day 7, their numbers declined in the ICAM-1/2-/- MedLNs as well as in the ICAM-1/2-/- lungs." (PMID 36895258, 2022). "In conclusion, our study revealed for the first time the increased percentage of NK cells, specifically CD49+ NK cells, upon infection and overexpression of LFA-1 in NK cells and ICAM-1 in an OT murine model." (PMID 36206304, 2022). "Multiple vascular adhesion proteins were induced rapidly during infection, such as CADM1, ICAM1, and VCAM1." (PMID 35913192, 2022). "Collectively, it is evident that various microbes exploit host ICAM-1/LFA-1 in cell-to-cell transmission and infection, thus, providing a robust pathway to mitigate microbial infection and persistence." (PMID 35316427, 2022). "Infection with A7UF induced an increased expression of Ccl2, Icam1, Tgfb1, Eng, and matrix metalloproteinase (Mmp) 2 and 9 with no change in the expression of the tissue inhibitor of metalloproteinase (Timp)." (PMID 36483452, 2022). "The host cells (EA.hy926) responded to the infection with an increased gene expression of CCL5, ICAM-1, IL-6, and CXCL10." (PMID 34490828, 2021).
infection (continued). "In both TLR4WT and TLR4mut mice, there was still a significant induction of BBB permeability, ICAM-1, MMP-2 and CCL-2 in the brains during VEEV TC-83 infection." (PMID 33487119, 2021). "The physical interactions between HDF/DCs via surface molecules such as Thy-1/Mac-1 (CD11a-CD18) or ICAM-1/LFA-1 (CD11b-CD18) induce activation of both HDF and DCs, promoting the secretion of type I interferons previous to the infection." (PMID 33193307, 2020). "To validate these findings in mice, we infected primary HUVEC cultures with different doses of O. tsutsugamushi (3 and 10 MOI) and found a dose-dependent increase in ICAM1 and IL8/CXCL8 transcripts at 24 h post-infection." (PMID 32119672, 2020). "The release of select inflammatory proteins (IL6, IL8, CSF3, IL1β, CXCL10, and ICAM1) into the culture medium of HEKs and SCC cells following infection with C. t." (PMID 31912662, 2020). "ICAM-1 is known for its capacity to adhere the parasite MIC2, which favors host cell infection by the parasite." (PMID 32231666, 2020). "In our study, reduced expression of IFNγ, LTα, ICAM-1, CXCL9 and CXCL10 were in line with impaired recruitment of CXCR3+CD8+ T cells to the brains of mice that received BCG before PbA infection." (PMID 33316929, 2020). "Within 12 h of infection, we observed an almost complete shift of the CD31−CD45− FLS population towards ICAM-1+VCAM-1+ cells, indicating that more than 90% of all FLS expressed these adhesion molecules at a high level." (PMID 33117382, 2020). "Intracellular adhesion molecule -1 (ICAM-1) knockout mice, which anatomically have a less leaky BBB, exhibit reduced severity of the symptoms and mortality after V3000 infection and demonstrate marked reduction in inflammation of the brain microvasculature." (PMID 30781656, 2019). "The release of HMGB1 also increases the expression of ICAM-1, VCAM-1 and pro-inflammatory cytokines in endothelial cells, suggesting a propagation of the immune response during infection or injury by HMGB149." (PMID 31748599, 2019). "CVA21 infection can be ablated with anti-ICAM-1 antibody blockade, and anti-DAF antibodies can block 50% of CVA21 infection of ME4405, with SK-Mel-28 being unaffected." (PMID 31100962, 2019). "The expression of the intercellular adhesion molecule 1 gene (ICAM1), which contributes to recruitment of circulating leukocytes to infection sites and stabilizes cell-target interactions, was also upregulated at W14." (PMID 31555289, 2019). "The MIF inhibitor ISO-1 inhibited ICAM-1 production in endothelial cells, and monocyte-endothelial cell adhesion was induced by P. gingivalis ATCC 33277 infection." (PMID 29482504, 2018). "The results revealed that P. gingivalis ATCC 33277 infection (MOI = 100:1, 24 h) induced a significant increase in ICAM-1 expression." (PMID 29482504, 2018). "After KFDV infection of the cells (MOI 10), ICAM1 was most noticeably expressed (with 20.0% ICAM1–positive cells), whereas E-selectin and VCAM1 production were not so prominent (10.7 and 9.8% positive cells, respectively)." (PMID 30401896, 2018). "Based on antibody availability, we selected five proteins (FCGR3, FCGR1, CD274, ICAM1, SLAMF8) to profile 24 h after infection with pseudotyped HIV-1 by flow cytometry in CD14- CD11cHi HLADR+ DCs from our cultures." (PMID 29378643, 2018). "While expression of P-selectin, ICAM-1, and VCAM-1 were increased in infected WT mice, the expression of these molecules was unchanged by the infection in Gas6−/− mice." (PMID 29967614, 2018). "The effect of binding to ICAM-1 or CD36 in pathology and sequestration in vivo during a blood-stage infection with P. chabaudi in mice was investigated." (PMID 28468674, 2017). "Compared to uninfected endothelial cells, the signal intensities of ICAM-1 and ICAM-2 were elevated by infection with either L. interrogans sv." (PMID 28750011, 2017).
infection (continued). "The levels of MIP1α/Ccl3, IL-1, and IFNγ-inducible factors, such as ICAM-1, IP10/Cxcl10 and Cxcl9 were all increased in the chronic phase of the infection." (PMID 28787450, 2017). "However, overall OM-85 might reduce the infection rate in vivo by modulation of ICAM1 expression." (PMID 29182620, 2017). "Despite having similar 3D structures, some bind members of the low-density lipoprotein receptor family, some ICAM-1, and some use CDHR3 for host cell infection." (PMID 27251607, 2016). "In the present study, pretreatment of epithelial cells with EM900 reduced ICAM-1 expression and the production of pro-inflammatory cytokines after RV14 infection." (PMID 26462747, 2015). "After infection of HCAEC with T. cruzi, we observed increased cell surface expression of intercellular adhesion molecule‐1 (ICAM‐1), vascular cell adhesion molecule‐1 (VCAM‐1), and E‐selectin prior to the observed increase in PAF production." (PMID 24744875, 2014). "The potential exists that ICAM-1 expressed on the surface of the RABV particle enhances and/or prolongs virus:cell interactions, leading to greater virus uptake, infection and activation of B cells that constitutively express LFA-1." (PMID 24489846, 2014). "Analysis of CAMs response to Eg101 demonstrated that mRNA of all three CAMs, ICAM-1, VCAM-1 and E-selectin were induced in infected HBMVE cells at 48 hrs time point, which further increased at 72 hrs after infection." (PMID 25036379, 2014). "As expected, blockade of ICAM-1 with the mAb RM3A5 not only inhibited the formation of mDC-CD4+ T-cell conjugates, but also impaired the mDC-mediated trans-infection of HIV-1 to CD4+ T lymphocytes by 60% to 70% (p < 0.05)." (PMID 23590845, 2013). "Increase in the mRNA levels of ICAM-1, VCAM-1 and MCP-1 was observed on addition of CRP or high glucose and infection with IGFBP-3 significantly decreased these levels." (PMID 23383064, 2013). "On the contrary, binding of ICAM-1 to LFA-1 is necessary for both the interaction between mDC and primary CD4+ T cells and efficient mDC-mediated HIV-1 trans-infection." (PMID 23590845, 2013). "Our results thus highlight the role of ICAM-1 in reducing HIV-1 dissociation from lymphoid cells, a process that appears to limits productive infection of these cells and engineered cell lines." (PMID 22970312, 2012). "Infection also induced the expression of co-stimulatory molecules such CD40, CD83, CD86, adhesion molecules (CD38, Itga5, and ICAM1), and tissue invasion molecules such as MMP12 and MMP14." (PMID 22928052, 2012). "A series of publications by the Tremblay laboratory has nicely delineated the effect of ICAM-1 on HIV-1 binding, uptake and infection in lymphoid cells expressing LFA-1." (PMID 22970312, 2012). "In spite of the marked enhancing effect of ICAM-1 on HIV-1 binding and infection of T cell lines and primary CD4+ T cells, the virus fusion with primary CD4+ T cells appears to be only slightly (1.2-fold) enhanced by this adhesion molecule." (PMID 22970312, 2012). "Bafilomycin A1 reduced the viral titer of RV14 and inhibited the production of cytokines, including IL-1β, IL-6, IL-8, and TNF-α, and ICAM-1 before and after RV14 infection." (PMID 22966430, 2012). "Accumulation of leukocytes at the site of local injury or infection of endothelial cells is dependent on the interaction of circulating leukocytes with vascular adhesion molecules, such as E-selectin, VCAM-1, and ICAM-1." (PMID 23209478, 2012). "Taken together, these data demonstrated that the enhanced ICAM-1 expression and virological synapses account for increased HIV-1 trans-infection mediated by fungus-stimulated MDDCs." (PMID 22110688, 2011). "Transfer infection of polarized epithelial cells is restricted to the basolateral surface, even though conjugate formation via LFA-1/ICAM-1 interactions is possible at the apical surface." (PMID 21573183, 2011).